ATM (ATM serine/threonine kinase)
Diseases named in the same sentence as ATM in open-access papers (continued):
Sharing a sentence is not in itself a finding about the gene and the disease.
cancer (continued). "Germline variants in the HR pathway, comprising at least 10 genes, such as BRCA1, BRCA2, ATM, BARD1, BRIP1, CHEK2, NBS1(NBN), PALB2, RAD51C, and RAD51D, lead to inherited susceptibility to specific types of cancers, including those of the breast, ovaries, prostate, and pancreas." (PMID 35008774, 2021). "17% of patients had germline protein-truncating variants (PTVs), with biallelic inactivation happening in ~4% of these patiences due to further somatic alteration on top of a germline PTV affecting known cancer-predisposition genes (such as BRCA1, BRCA2, and ATM)." (PMID 34097189, 2021). "Moreover, ATM supports the maintenance of cancer stem cells (CSCs) with the capacity to convert into EC-like cells to form VM, which in turn provides a niche to protect and nourish CSCs." (PMID 34483751, 2021). "As hypoxia and increased ROS stress frequently occur in solid tumors, ATM may promote cancer cell survival in some scenarios by stabilizing HIF1α and reducing ROS levels." (PMID 34070860, 2021). "In particular, the hypersensitivity of ATM-mutated cancers to ATR inhibition could be driven by over-lapping and redundant functions of ATM and ATR kinases, given that there are over 700 suggested ATM/ATR substrates harbouring S/T-Q motifs." (PMID 34329458, 2021). "ATM and ATR are conserved regulators of the DNA damage response linked to cancer." (PMID 33742106, 2021). "Several ATM inhibitors are now under investigation for cancer therapy." (PMID 34977872, 2021). "However, in some advanced stage tumor cells, ATM signaling is increased and confers remarkable advantages for cancer cell survival, resistance to radiation and chemotherapy, biosynthesis, proliferation, and metastasis." (PMID 34070860, 2021). "Comprehensive DNA sequencing efforts identified ~4,000 cancer-associated mutations in ATM/ATR; however, their cancer implications remain largely unknown." (PMID 33742106, 2021). "Therefore, cancers with loss‐of function mutations in HR pathway components such as BRCA1, ATM, ATR, RAD51, and FANC genes are susceptible to treatment with PARP inhibitors." (PMID 33660437, 2021). "Moreover, the specific ATM inhibition by KU-55933 leads to tachyzoite cell cycle arrest in the G1 phase, as occurs when cancer cells are treated with the same compound." (PMID 34421876, 2021). "Together, these findings identify evolutionarily conserved ATM, ATR, and Mec1ATR residues involved in diverse aspects of the enzyme function and provide fresh insights into the elusive genotype-phenotype relationships in ATM/ATR and their cancer-associated variants." (PMID 33742106, 2021). "We wished to examine whether the ATM and ATR residues mutated in a specific cancer type might localize to a distinct region(s) of the respective enzyme complexes." (PMID 33742106, 2021). "Among the 163 ATM residues examined, only three are common to the three cancer types." (PMID 33742106, 2021). "HMGA1 promotes ATM expression and enhances cancer cell resistance to genotoxic agents." (PMID 34716319, 2021). "ATM is a very large gene that is frequently mutated in cancer but the mutations occur throughout the gene with no hotspots." (PMID 33782497, 2021). "Heterozygous ATM mutations are associated with a five-fold higher risk of BC in subjects under 50 years of age and are well classified in the COSMIC (Catalogue of Somatic Mutations in Cancer) database." (PMID 34068084, 2021). "The ataxia-telangiectasia mutated (ATM) gene plays a central role in DNA damage response and DSB repair, and its germline mutation is known to produce a specific syndrome, as well as increasing the risk of developing several types of cancer, including PC." (PMID 34358103, 2021).
cancer (continued). "In addition, as many as 4% of these individuals have germline pathogenic mutations in cancer predisposition genes other than BRCA1 and BRCA2 on MGPT (i.e. CHEK2, PALB2, ATM, NBN, PTEN, etc.)." (PMID 33541411, 2021). "Thus, forming an ATM-phosphorylated MDC1-RNF8 protein complex is a critical determinant of cisplatin resistance in cancer cells defective in BIN1 expression." (PMID 34948122, 2021). "Indeed, MELK was shown to increase the tolerance of cancer cells to the DNA damage response by inhibiting the phosphorylation of ATM." (PMID 33431809, 2021). "Inhibitors of ATR, ATM and DNA-PK have been studied in many different cancer types." (PMID 34298632, 2021). "From WikiPathways, we identified major receptors targeted by epinephrine and norepinephrine and nuclear receptors in lipid metabolism and toxicity, while the chemokine signaling pathway and the ATM signaling pathway were identified from the WikiPathways Cancer database." (PMID 33410284, 2021). "Other ATM LOF variants were found in individuals without personal or family history of other cancers or for whom this information was not available." (PMID 34262154, 2021). "Since the BIN1 gene rarely mutates in human cancers, our results suggest that simultaneous inhibition of PARP1 and ATM provokes a new BRCAness-independent synthetic lethal effect and ultimately re-establishes cisplatin sensitivity even in platinum-refractory cancer cells." (PMID 34948122, 2021). "While ATM and DNA-PK expression may be lost in human cancer, ATR expression is generally maintained, although mutations and reduced expression levels are sometimes observed." (PMID 34298632, 2021). "It is well known that inhibition of ATM sensitizes cancers to genotoxic exposure." (PMID 34068585, 2021). "In fact, ATM-mediated activation of Akt can induce cancer cell survival in certain scenarios." (PMID 34070860, 2021). "Furthermore, the addition of the ATM kinase-specific inhibitor KU55933 or another ATM/ATR dual inhibitor CGK733, caused the increase of apoptosis in these cancer cells." (PMID 33912571, 2021). "For example, in the future, comprehensive profiling of a panel of resistance pathways may guide patient-specific administration of rationally targeted combination therapy (e.g., PARPi plus ATM inhibition in 53BP1 mutant cancers)." (PMID 34572943, 2021). "High expression of ATM was found to increase the efficiency of DNA damage repair and promote radiation resistance, and ATM protein expression correlates with radioresistance in human cancer." (PMID 34766149, 2021). "Therefore, ATM-based anti-cancer therapy should be carefully selected and tailored based on the characteristics of the tumors to achieve significant and long-lasting therapeutic effects." (PMID 34070860, 2021). "BRCAness allows for the expansion of the somatic lethality approach to tumors carrying deficiencies in tumor suppressor genes involved in homologous recombination (HR) defective cancers, possessing BRCA1, BRCA2, ATM, ATR, FANC, RAD51, BRIP1, or PALB2 mutations." (PMID 34639169, 2021). "The modified query returned many more disorders, including cancers that are not explicitly associated with ATM." (PMID 34379637, 2021). "Therefore, instead of directly targeting neoplastic MYC, our study theoretically justifies clinically approved PARP and ATM inhibitors that can be co-used to re-establish platinum sensitivity even in platinum-refractory cancer cells." (PMID 34948122, 2021).
cancer (continued). "Earlier in the review, we discussed the concept of targeting ATR in ATM mutant cancers." (PMID 34572943, 2021). "These include connecting cancers with HRD or STAG2 deficiency with PARP inhibitors, epigenetic dysregulation with histone deacetylase or EZH2 inhibitors, and DNA checkpoint abnormalities with ATM or ATR inhibitors, to name a few." (PMID 34101093, 2021). "Cancer cells may compensate the loss of ATM by upregulating ATR, indicating that ATR inhibitors may display efficacy in ATM-deficient tumors, including PCa." (PMID 33672917, 2021). "In humans, germline mutations in ATM and ATR lead to Ataxia-Telangiectasia (A-T) and Seckel syndrome, respectively, characterized by a constellation of symptoms, including neurodegeneration, cancer, diabetes, infertility, and microcephaly." (PMID 33742106, 2021). "Chk2 can be overexpressed in cancer cells and phosphorylated by p-ATM." (PMID 32560563, 2020). "Our work might provide a new evidence supporting the potential of ATM as a potential target of cancer therapy." (PMID 32174787, 2020). "Taken together, cancers with ATM aberrations may rarely respond to PARPis, and the response is, in general, more limited compared with the activity in BRCA1/2 tumors." (PMID 33233320, 2020). "ATM is altered in 5.58% of all cancers and CRC is one of the important cancer types in these." (PMID 32283892, 2020). "Our recent studies have revealed that in ATM-deficient cancer cell lines, olaparib is cytostatic not cytotoxic and that combination of olaparib with an ATR inhibitor is needed to induce cell death." (PMID 32183301, 2020). "Cancer susceptibility genes (CHEK2, PRF1, ATM, AKAP13, SLC26A11) were also observed." (PMID 33218058, 2020). "Together, these findings led us to propose that cancers cell may adapt to radiation and develop resistance to irradiation through increasing the expression of ATM, which could accelerate DSBs repair efficiency and reduce radiation-induced cell apoptosis." (PMID 32174787, 2020). "Segregation with the cancer phenotype in certain variants was incomplete in some families: such as the family with c.94_95delGT RAD51D mutation and the family with c.3663G>A ATM variant." (PMID 32756499, 2020). "While ATM, BRCA, and POLQ mutations were similarly prevalent in both cancer types, adenocarcinoma patients had a high frequency to mutations effecting FANCM (8.9%) and FANCD2 (5.6%), comprising a majority of the difference between the two cancers in overall HR mutation rate." (PMID 33214570, 2020). "Five cryptically spliced genes (ANKHD1, ATM, FOXP1, MAP3K7, and TTI1), identified in previous transcriptomic analyses in SF3B1-mutated patients, were analyzed in different cancer types." (PMID 33585229, 2020). "Many studies suggest that the status of the DDR pathway affects cancer cells’ response to chemotherapy, with loss of DDR elements increasing the sensitivity to DNA-damaging platinum and PARP inhibition, such as BRCA1, BRCA2, BARD1, ATM, and PALB227." (PMID 32457312, 2020). "Cancer cells undergoing apoptosis can not only recover from the brink of death through anastasis, but they can also secrete tumor promoting factors which is initiated by caspase-3 and involves the ATM-dependent DNA damage response." (PMID 32075223, 2020).
cancer (continued). "Recently, it has been shown that ATM‐mediated phosphorylation of RAGE is central for DNA‐DSBs repair, as the absence of timely DNA repair or the absence of RAGE (RAGE−/− mice model) is causatively linked to tissue fibrosis and cancer." (PMID 32338774, 2020). "Interestingly, loss of RAD52 has been shown to reduces cancer predisposition and increases the lifespan of adenomatous polyposis coli (APC)- or ataxia-telangiectasia mutated (ATM)-deficient animals." (PMID 32355220, 2020). "In the following paragraphs, we will detail the activation pathway, and compare the unique features of mouse models with null or KD mutations of ATM, ATR and DNA-PKcs and attempt to summarize their common features and their implications in human disease and cancer therapy." (PMID 32015826, 2020). "Common genetic mechanisms, especially those underlying cell cycle turnover and protein regulation such as those involving SNCA, PARK2, PARK8, ATM, PTEN, PINK1, and MC1R have been implicated in both neurodegeneration and cancer and perhaps explain this association." (PMID 32547471, 2020). "Of 21 cancers examined after neoadjuvant chemo-radiotherapy, one patient had tumoral ATM loss and no histologic evidence of tumor response at the time of surgery." (PMID 33224881, 2020). "In addition, genetic studies identified an association between late radiation-induced fibrosis and polymorphisms in the ATM, TGFB, ERCC1, and ERCC5 genes for cancer patients who had been treated with radiotherapy." (PMID 32775415, 2020). "In addition, the ATM/ATR/CHK1 pathway has been shown to be essential for upregulation of PD-L1 on cancer cells after treatment with DNA-damaging agents." (PMID 33224881, 2020). "The ATM is involved in resistance of chemotherapy in cancer cells." (PMID 32503307, 2020). "Finally, our data suggests a strategy for the design of novel small molecules that can modulate the activity of Rad50 and interrupt ATM signaling, possibly providing another approach for synthetic lethality in anti-cancer therapies." (PMID 31889185, 2020). "Moreover, the target genes of PTEN and ATM, as well as the differentially expressed miR-654-3p, were found related to the pathways of central carbon metabolism in cancer and cell cycle." (PMID 33178319, 2020). "Interestingly, knock-out of ATM can reverse this axis to enhance the sensitivity of cancer cells to CP therapy." (PMID 32503307, 2020). "Proficient ATM-mediated pathways act as robust anti-cancer barriers." (PMID 30746633, 2019). "Rs189037 (G>A) is an important functional variant with ataxia telangiectasia mutated (ATM) gene, which might affect ATM’s expression involvement in several human cancers." (PMID 31201228, 2019). "Our study highlights that there is a significant association between ATM rs189037 and cancer risk in non-smokers, rather than in smokers." (PMID 31201228, 2019). "Our work not only provides a new insight into the pathogenic role of ATM variants in occurrence of cancer, but also supports the distinct molecular characteristics of cancers between smokers and non-smokers." (PMID 31201228, 2019). "In light of these findings and because ATM has been linked to controlling DSB resection, a key early step in HRR, it has been suggested that hypersensitivity of ATM-deficient cancer cells to PARP inhibitors, TOP1i, and other S-phase DNA-damaging agents arises from HRD16." (PMID 30622252, 2019). "Based on the data presented in the literature, the ATM/MRN-coordinated DNA damage response network can be usually activated in early stages of different kinds of cancer, which there has been increasing evidence that suggests the DNA breakage and oncogene-induced replication stress are partial." (PMID 30975222, 2019).
cancer (continued). "Previous studies have revealed that the DNA-DSB repair ATM-signaling pathway was upregulated and persisted for several days after RT, and that upregulated DNA repair signaling may suppress apoptosis of cancer cells." (PMID 31430901, 2019). "Our findings highlight that ATM rs189037 significantly increases cancer susceptibility in non-smokers, rather than in smokers." (PMID 31201228, 2019). "The level of cancer risk associated to PALB2 pathogenic variants is known to be low in comparison to BRCA2 pathogenic variants, but enough to propose a clinical management of the familly contrary to other low risk genes, notably CHEK2 1100delC and ATM." (PMID 29707112, 2018). "The blockade of ATM with KU55933 prevented the (S)-crizotinib-induced Akt activation, a finding consistent with reports that ATM is a major regulator of full Akt activation, its inhibition correlated with suppression of Akt-dependent pro-survival signals in cancer cells." (PMID 29855474, 2018). "Our finding that (S)-crizotinib activated the ATM–Akt pathway suggested that pro-survival signals could, at least in part, masked/countered anti-cancer growth activity exerted on GC cells." (PMID 29855474, 2018). "This mini-review aims to shed new light on the complexity of these new molecular circuits through which ATM may modulate cancer progression and to highlight a novel role of ATM in the control of proteostasis." (PMID 29616191, 2018). "Our identification of linker histone H1.2 as a novel PARP1 downstream target may help us better understand the functional mechanisms of ATM inhibition in cancer treatment and may lead to the discovery of new promising targets for cancer therapy." (PMID 29844578, 2018). "Therefore, we used a pharmacological inhibitor (KU55933) to test the potential contribution of ATM signaling to HORMAD1 regulation in cancer cells." (PMID 30333500, 2018). "Additionally, literature clearly reveals that ATM expression is downregulated in several forms of cancer including that of breast and lung." (PMID 29755656, 2018). "Moreover, ATM inhibition enhances the sensitivity to the radiation therapy that generates ROS in cancer cells." (PMID 29770165, 2018). "What is the mechanism for the constitutive activation of ATM in cancer?" (PMID 30456351, 2018). "Furthermore, ATM sustains cancer stem cells survival by promoting the autophagic flux and ATM kinase activity is enhanced in HER2-dependent tumors." (PMID 29616191, 2018). "The dissociation of HP1α from H3K9me3 by SYCE2 shown in our study might be one of the mechanisms for the increased steady-state ATM activity in cancer." (PMID 30456351, 2018).